TNF (tumor necrosis factor)
Diseases named in the same sentence as TNF in open-access papers (continued):
Sharing a sentence is not in itself a finding about the gene and the disease.
experimental autoimmune encephalomyelitis (continued). "In mice with experimental autoimmune encephalomyelitis, myelin-specific Tregs were detected in the brain and spinal cord, but their function was inhibited by TNF and IL-6; these two cytokines are expressed in the rJ2.2-infected CNS." (PMID 25102154, 2014). "They showed that ESA decreased the peak clinical severity of experimental autoimmune encephalomyelitis in a dose-dependent manner, with a simultaneous marked decrease of TNF and the pro-inflammatory cytokine IL-6 in the spinal cord." (PMID 22583484, 2012). "It has been reported that repeated injections of DCs matured with TNF-α induces antigen-specific protection against experimental autoimmune encephalomyelitis (EAE) in mice." (PMID 23300516, 2012). "Specifically, overexpression of TNF leads to demyelinating disease and neutralization of TNF with anti-TNF antibodies or receptor fusion proteins is protective in experimental autoimmune encephalomyelitis (EAE) transgenic mouse models." (PMID 18925972, 2008). "Similarly, TNFα expression is upregulated in experimental autoimmune encephalomyelitis (EAE), and administering TNFα to these mice has been shown to exacerbate the disease." (PMID 39339700, 2024). "IL-β and TNF are increased in the brain of MS patients and contribute to induce the changes in synaptic plasticity occurring in MS patients and its animal model, the experimental autoimmune encephalomyelitis (EAE)." (PMID 29861718, 2018). "Moreover, in the same study, exogenous ghrelin suppressed spinal cord levels of TNF-α, IL-1β and IL-6 mRNA in a mouse model of experimental autoimmune encephalomyelitis (EAE)." (PMID 23509933, 2013). "Moreover, in vivo studies in animal models of experimental autoimmune encephalomyelitis (EAE) have demonstrated that blocking of TNF-α by neutralizing antibodies, or drugs, ameliorates the disease." (PMID 21034511, 2010). "Studies were carried out in vivo in mice on tumor necrosis factor-alpha (TNF-α), and the development of experimental autoimmune encephalomyelitis (EAE) was evaluated." (PMID 38998660, 2024). "In experimental autoimmune encephalomyelitis (EAE), activated M1 microglia upregulated CCL-2, which facilitated the recruitment of circulating monocytes to the injured sites, as well as TNF and iNOS, which contributed to inflammation." (PMID 36558562, 2022). "In these studies, using an experimental autoimmune encephalomyelitis model, 2-BFI administration reduced the expression of inflammatory cytokines, including interferon-g (IFN-γ), tumor necrosis factor-α (TNF-α) and microglial activation." (PMID 34573297, 2021). "In both MS and its animal model, experimental autoimmune encephalomyelitis (EAE), autoreactive T cells cross the impaired BBB in a tumor necrosis factor-α (TNFα)- and interferon-γ (IFNγ)-driven immune response." (PMID 30704100, 2019). "Induction of experimental autoimmune encephalomyelitis (EAE) in transgenic mice expressing a dominant-negative interferon-γ receptor under the human glial fibrillary acidic protein promoter (GFAPγR1Δ) causes severe non-remitting disease associated with sustained TNF." (PMID 29690885, 2018). "On the other hand, tolerogenic DCs have been used to restore tolerance in experimental autoimmune encephalomyelitis and CIA by preventive injections of TNF-maturated DCs or by therapeutic injection of LPS-stimulated DCs in mice with established CIA." (PMID 23818913, 2013). "This is similar to what was observed in rodent models of experimental autoimmune encephalomyelitis (EAE), where expression of IL-1β activated and translocated NF-ΚB to the nucleus and induced expression of inflammatory cytokines, IL-1β and TNF-α, as well as the IL-10." (PMID 38938553, 2024). "In experimental autoimmune encephalomyelitis, BBG-dependent P2 × 7R antagonism resulted in decreased BBB damage with normalized levels of PDGFβR and claudin-5 and pro-inflammatory cytokines, IL-1β, IL-6, and TNF-α." (PMID 39342243, 2024).
experimental autoimmune encephalomyelitis (continued). "In experimental autoimmune encephalomyelitis (EAE), GA positively regulates inflammation by increasing anti-inflammatory IL-4, IL-10 and IL-13, while the pro-inflammatory cytokines IL-6, IL-12 and TNF-α are reduced." (PMID 36831209, 2023). "Likewise, in the preventative and therapeutic experimental autoimmune encephalomyelitis model (EAE), high doses of VPA (500 mg/kg) reduced transcript levels of TNFα, IL-1β and iNOS in the EAE spinal cord." (PMID 36412793, 2022). "A protective effect of curcumin against mitochondrial injury and OL/neuronal apoptosis has been shown in experimental autoimmune encephalomyelitis (EAE), an animal model of MS6, suggesting that a similar mechanism could occur also in TNF-α treated OPs." (PMID 33654147, 2021). "Several studies have shown increased levels of the cytokines TNF-α, IL-1β, and IL-6 in the DRG of animals with chronic pain induced by chemotherapeutic paclitaxel, chronic constriction of the sciatic nerve, experimental autoimmune encephalomyelitis, operation, or inflammation." (PMID 33355900, 2021). "Similarly, using the myelin oligodendrocyte glycoprotein (MOG)-induced experimental autoimmune encephalomyelitis (EAE) model, it has been shown that TNFα KO mice developed more severe EAE, while TNFα treatment ameliorated the disease." (PMID 18380898, 2008). "However, characterizing the precise mechanisms underlying TNFα signaling in human MS has proved difficult, and thus studies of MS animal models, such as experimental autoimmune encephalomyelitis (EAE), have led to hypotheses regarding the actions of TNFα." (PMID 41480143, 2025). "In the experimental autoimmune encephalomyelitis (EAE), the rodent model of MS, it was recently demonstrated that the activation of microglia and the inflammatory cytokines released from infiltrating lymphocytes, especially TNF-α, are able to alter synaptic transmission." (PMID 22558238, 2012). "Indeed, at the beginning of demyelination, such as in experimental autoimmune encephalomyelitis (EAE), a mouse model of MS, it has been reported that tumor necrosis factor (TNF) secreted by ASTs or endothelial cells may cooperate with TNF receptors on the surface of OLs to damage the BBB." (PMID 36370324, 2023). "In line with our findings, CD200Fc treatment significantly decreased the production of TNF and IL-6 but not of IL-10 or TGF-β in microglial cells of mice with experimental autoimmune encephalomyelitis." (PMID 26891688, 2016).
pulmonary hypertension (96 papers, 2007 to 2026). Increased pressure within the pulmonary circulation due to lung or heart disorder. "TNF-α inhibitors reduce the systemic inflammation and improve the endothelial function, decreasing the risk of pulmonary arterial hypertension progression and of acute cardiovascular and/or cerebrovascular events." (PMID 38388392, 2024). "IL-1, IL-6 and TNF-α protein levels were shown to be closely associated with PI3K/Akt signaling pathway activation in early stages of monocrotaline-induced pulmonary hypertension in rats." (PMID 36670454, 2023). "TNFα inhibitors reduce systemic inflammation, improving the endothelial function and decreasing the risk of pulmonary arterial hypertension progression." (PMID 36209279, 2022). "The over-expressing TNF-alpha transgenic mice that develop an array of connective tissue diseases has been associated with interstitial lung disease and pulmonary hypertension, particularly in female mice." (PMID 33577605, 2021). "IL-18 and TNF-α are pro-inflammatory cytokines previously reported to be associated with BPD or pulmonary hypertension in preterm infants or experimental models of BPD27–30." (PMID 33888735, 2021). "The TNF-α inhibitor can improve endothelial functions and decrease the risk of pulmonary arterial hypertension in SSc." (PMID 34943909, 2021). "Elevated serum TNF-α level in patients with SSc was associated with pulmonary fibrosis, decreased vital capacity, and pulmonary arterial hypertension." (PMID 34943909, 2021). "We also noted that IL-6 and IL-13 levels were increased in patients with pulmonary hypertension, and that TNFα levels were associated with the presence of renal crisis." (PMID 19799786, 2009). "In an in situ perfusion experiment in piglets, endotoxins caused only pulmonary hypertension and neutropenia, while the levels of tumor necrosis factor α (TNF-α), interleukin (IL) -6, and nitric oxide (NO) were elevated when perfused into the lungs alone, without causing pulmonary edema." (PMID 39935473, 2025). "Moreover, proinflammatory mediators, such as tumor necrosis factor-α (TNF-α), IL-1β, IL-6, and IL-10, also induce EndoMT implicated in pulmonary hypertension." (PMID 35681530, 2022). "The purpose of this present study was to reveal the regulatory effects of trimethoxystilbene on the serum levels of nuclear factor kappa B, interleukin-6, and tumor necrosis factor-α in a rat model of pulmonary artery hypertension and to explore the possible underlying mechanisms." (PMID 31886168, 2019). "Previous studies have established that lesions due to pulmonary arterial hypertension could cause activation of macrophages which subsequently secretes several cytokines including IL-6 and TNF-α." (PMID 26391589, 2015). "A previous study by Nick Morrell’s laboratory revealed that TNFα promotes pulmonary hypertension by repressing BMPR-II signaling and enhancing BMP6, which, in turn, stimulates SMC proliferation via ALK2 and ACTR-IIA." (PMID 39273443, 2024). "SAS-induced chronic intermittent hypoxia stimulates the secretion of inflammatory cytokines like IL-6, TNF-α, and CPR, and it causes pulmonary hypertension." (PMID 35871643, 2022). "For instance, astragalus polysaccharides decrease levels of the inflammatory cytokine TNF-α, IL-1β and IL-6 to resist pulmonary artery hypertension induced by MCT." (PMID 35033157, 2022). "In an animal model of pulmonary arterial hypertension, colchicine administration suppressed smooth muscle cell proliferation, elevated apoptosis and diminished the protein expression of inflammation (TNF-α and NF-κB)." (PMID 35204113, 2022). "Pulmonary arterial hypertension patients exhibit high levels of the cytokines IL-1β and TNFα that in the presence of TGFβ induce EndMT in pulmonary arterial ECs in vitro." (PMID 32226439, 2020).
pulmonary hypertension (continued). "Earlier studies showed that, in general, patients with pulmonary hypertension demonstrated TNFα serum levels within the normal range, but had increased serum levels of IL-1 beta and IL-6 in severe primary pulmonary hypertension." (PMID 31024947, 2019). "In the previous experiment, resveratrol treatment decreases the expression of inflammatory cytokines such as TNF whose activation is related to the development of pulmonary hypertension in MCT-treated rat29,30." (PMID 28790372, 2017). "Several reports have demonstrated that the cytokines interleukin (IL)-1β, IL-6, and tumor necrosis factor-α, released by activated macrophages, play an important role in the pathogenesis of pulmonary arterial hypertension (PAH)." (PMID 29273073, 2017). "Deletion of TNFα in mice inhibits intimal hyperplasia after carotid artery injury, while an increased expression of TNFα aggravates pulmonary hypertension in mice." (PMID 24804145, 2014). "Liu and colleagues found that EP ameliorates monocrotaline-induced pulmonary arterial hypertension and reverses pulmonary vascular remolding in rats by inhibiting the release of TNF-α and IL-6 and by reducing the expression of endothelin-1." (PMID 25470819, 2014). "TNF-α expression level and activity can be up-regulated under hypoxia, inflammation, and pulmonary hypertension." (PMID 23613714, 2013). "For example, excessive release of cytokines, such as TNF-α, in pigs is known to induce pulmonary hypertension and cardiac depression." (PMID 22587828, 2012). "In addition, different drugs can induce sarcoid-like reactions, examples of these are TNF-α inhibitor, interferon therapeutics, immune checkpoint inhibitors, cancer-targeted therapies, and pulmonary hypertension drugs." (PMID 41328180, 2025). "The effects of running on the lung could also be evaluated in the context of cardiac disease as well, as severe and lethal pulmonary arterial hypertension and right ventricular hypertrophy is inherent in sedentary TNF-Tg mice and may be modified by exercise." (PMID 36732826, 2023). "However, the mechanism by which IL-6 and TNF-α involved in pulmonary hypertension formation is unclear." (PMID 33971931, 2021). "Besides, As-IV improved pulmonary function via suppressing the secretion of IL-6 and tumor necrosis factor-alpha (TNF-α) in the chronic hypoxia-induced pulmonary hypertension model." (PMID 34482800, 2021). "Studies have shown that mice overexpressing TNF-α had right ventricular hypertrophy and pulmonary hypertension and that TNF-α increased endocan in rat lung microvascular endothelial cells; conversely, endocan knockdown attenuated the damage induced by TNF-α in these cells." (PMID 34064667, 2021). "These previous studies suggest that IL-6, TNF-α, and IL-1β may be actively involved in pulmonary hypertension." (PMID 31815093, 2019). "TNFα plays an important role in the development of pulmonary hypertension, even though the concrete mechanisms remain unknown, but the evidences are mounting." (PMID 31024947, 2019). "Moreover, both IL-6-overexpressing mice and TNF-α-overexpressing mice induced spontaneously pulmonary hypertension and pulmonary vascular remodeling, while IL-6 knockout inhibited the development of pulmonary hypertension induced by chronic hypoxia." (PMID 31815093, 2019). "The differentially expressed cytokines, such as interleukin (IL)-1β, IL-8, IL-6 and chemokines like CCL5, RANTES, CXC3L1, fractalkine, monocyte chemoattractant protein (MCP)-1, and tumor necrosis factor (TNF-α) in pulmonary hypertension lesions affecting the heart, pulmonary artery and lung." (PMID 27275925, 2016). "TNF-α might play an important role in the development of pulmonary hypertension, even though the concrete mechanisms remain unknown." (PMID 26566389, 2015). "Potential conclusion: TNF-α might play an important role in the development of pulmonary hypertension, even though the concrete mechanisms remain unknown." (PMID 24739042, 2014).
pulmonary hypertension (continued). "Similarly, TNF-α over expression in alveolar type II cells resulted in chronic pulmonary inflammation, septal destruction, bronchiolitis and pulmonary hypertension." (PMID 24739042, 2014). "Injections of TNF-α to rats also increased vascular reactivity, which might contribute to pulmonary hypertension." (PMID 24739042, 2014). "Many inflammatory mediators [prostaglandin E1 (PGE1), PGE2, TNF-α, IL-1, IL-6, IL-8, nitric oxide, and platelet-activating factor], and pathophysiological conditions (hypoxia, pulmonary hypertension) have been shown to induce the expression of VEGF, angiogenesis, or both." (PMID 17631682, 2007). "In addition, pro-inflammatory mediators could be involved in CH-induced pulmonary hypertension because circulating tumor necrosis factor-α (TNFα) level was elevated in COPD patients." (PMID 28538666, 2017). "Numerous cytokines elevated in our study, such as IL-1α, IL-4, IL-5,IL-6, IL-7, IL-8, TNF-α were previously shown to involved in VOC-related acute clinical complications such as acute chest syndrome, pulmonary hypertension, and pulmonary thrombosis." (PMID 38361924, 2024). "It reduced the expression level of IL-6, TNF-α, and intercellular adhesion molecule-1 (ICAM-1) by regulating NF-kB signaling in pulmonary artery hypertension rat." (PMID 31024252, 2019). "A previous study showed that cilostazol therapy markedly suppressed the expressions of the TNF-α and MMP-9, two indicators of inflammation, in lung parenchyma of pulmonary arterial hypertension rats." (PMID 22897925, 2012). "In addition, we demonstrated that EndMT, which induces the inflammatory cytokines IL-1β, tumor necrosis factor α (TNF-α), and TGF-β in endothelial cells, can lead to pulmonary arterial hypertension." (PMID 37237925, 2023). "However, chemerin induced expression of TNF-α, which has been shown to contribute to pulmonary artery SMC remodeling in pulmonary arterial hypertension." (PMID 32848866, 2020). "The infusion of endothelin receptor antagonist ETR-P1/fl was proved effective in reducing serum nitrite and nitrate, TNF-alpha, and HMBG-1 in a piglet model of neonatal sepsis and also in reducing pulmonary hypertension and increasing mean arterial pressure and survival time." (PMID 30174784, 2018). "Likewise, with the exception of the pair pulmonary hypertension-COPD, “Apoptosis” pathways and related signaling events, such as “TNF signaling” or “Death receptor signaling” were also involved in most multimorbidity pairs." (PMID 25248857, 2014). "Bone marrow chimera experiments demonstrated that TNF-Tg mice with wild type (WT) bone marrow developed pulmonary hypertension while WT mice receiving TNF-Tg bone marrow did not, indicating that PAH is driven by stromal cell TNF production rather than by hematopoietic cells." (PMID 38731946, 2024). "Alteration in chemerin signaling has already been linked to other pro-inflammatory conditions or cytokines (including TNF-α, IL-1β, and IL-6) upregulating CMKLR1 and CCRL2 which are also known to play crucial roles in pulmonary artery remodeling in pulmonary hypertension." (PMID 32848866, 2020). "Other studies using TNF-α - antagonists, however, could not confirm an improvement of pulmonary hypertension." (PMID 24739042, 2014). "Moreover, COPD patients with pulmonary hypertension show significantly higher TNF-α and C-reactive protein levels than COPD patients without pulmonary hypertension, further corroborating the role of COPD as an inflammatory systemic disease." (PMID 24739042, 2014).